FAP (fibroblast activation protein alpha)
Diseases named in the same sentence as FAP in open-access papers (continued):
Sharing a sentence is not in itself a finding about the gene and the disease.
tumor (continued). "Immunohistochemical detection of FAP expression in tumor tissue and imaging might nonetheless point at progression of an early stage to a more aggressive disease." (PMID 34854061, 2022). "However, bulk expression data show that FAP expression in CMS4 tumours is significantly higher than that in CMS1 tumours." (PMID 35296803, 2022). "Therefore, the development of radioligands that target FAP/CAFs in the tumor microenvironment is useful for disease diagnosis, prognosis, and therapeutic management of various cancers." (PMID 35631416, 2022). "The FAP-positive fibroblasts were evaluated around the tumor cells and the stroma." (PMID 36051919, 2022). "Therefore, this novel FAPα activatable theranostic pro-photosensitizer with excellent biosafety displayed great potential for clinical precise tumor diagnosis and highly-specific PDT." (PMID 35664057, 2022). "Antigen FAP has already been developed as targeting cancer tracer, and it could show different xenograft tumor invasion into islets." (PMID 36051919, 2022). "Importantly, CAFs have been detected in NB, thus suggesting FAP targeting as a promising therapeutic strategy against this aggressive tumor." (PMID 36230765, 2022). "Together the data indicate partial loss of epithelial identity and cell-cell contact in FAP-expressing tumour cells, but no clear gain in expression of mesenchymal genes, which is in line with a ‘partial EMT’." (PMID 35296803, 2022). "FAP-2286 labeled with 177Lu displayed prolonged tumor retention (≥ 72 h) compared to FAPI-46 after injection in the HEK-FAP mouse model as measured by SPECT/CT image quantification, and yet maintained rapid system renal clearance as expected for small molecules." (PMID 35608703, 2022). "A tumor-cell-dependent enhancement in FAP expression by primary fibroblasts was demonstrated." (PMID 36230765, 2022). "Accumulating evidence has revealed that FAP + CAFs might provide a more immunosuppressive microenvironment to resist damage from immunocytes/radiotherapy/chemotherapy, resulting in increased tumor survival." (PMID 36092734, 2022). "FAPI-04 shows rapid internalization into FAP-positive tumors and fast clearance from the body, resulting in very fast accumulation at tumor sites (10 min after tracer administration); the effective tumor uptake after 24 h—100% higher for FAPI-04 than for FAPI-02." (PMID 35692767, 2022). "The fibroblast activation protein (FAP) can be seen as a very interesting candidate as it is not only expressed on several tumor types, but also on cancer-associated fibroblasts (CAFs) that are part of the tumor microenvironment (TME)." (PMID 36015148, 2022). "Moreover, the expression of FAP in peritoneal metastases was even higher than that in the corresponding primary tumours." (PMID 35296803, 2022). "Taken together, the data of this study hypothesized that the high expression of TGF-β might be one of the main drivers that induces CAFs to produce a high quantity of αSMA and FAP that prevent TILs to infiltrate tumor areas." (PMID 36685537, 2022). "Still, in molecular studies, FAP is strongly expressed in the CAFs, highly prevalent in stroma-high tumours, which could be an indication of a high number of binding spots for FAPI." (PMID 35482276, 2022). "We propose a hypothesis that neuropeptide FAP in HCC may be regulated by exosomes in the tumor microenvironment." (PMID 35186170, 2022). "Tumor cell–derived FGFBP1 induces FAPα expression in HSCs via the FGF2/FGFR1/ERK1/-2/EGR1 axis." (PMID 35951441, 2022). "Although alpha emitters have a higher LET (greater by a factor 500) and shorter ranges (50–100 μm), which may reduce toxicity burden and improve tumor cell killing, the role of 225Ac in FAP-targeted RPT remains unknown." (PMID 36178531, 2022).
tumor (continued). "The mechanism for these patterns of FAPα expression has not yet been elucidated, but it is expected to be associated with tumor invasion and lymph node metastasis in the presence of complex epithelial-stromal cross-talk at the invasive front of cancer." (PMID 34976180, 2022). "Combination with DB and FAP-IL-2v resulted in reduced tumor growth and improved survival." (PMID 36230765, 2022). "68Ga-FAPI is thought to be the potential broad-spectrum tumor PET agent targeting FAP." (PMID 39354964, 2022). "But FAP was expressed in 90% epithelial tumor tissues and 50–95% tumor stroma." (PMID 33816303, 2021). "Besides the higher tumor-to-background-ratios for each respective location, the FAP-targeted imaging had a higher detection rate for primary tumors and metastases in lymph nodes, lungs, brain and bone, as well as the liver." (PMID 34830898, 2021). "Consistent with previous works, we found FAP could be secreted by tumor cells and promote the cancer cell migration and invasion." (PMID 34035230, 2021). "Studies demonstrated IL6 derived from prostate cancer cells elicits pro-tumor FAP+CAF." (PMID 34760886, 2021). "68Ga-fibroblast activation protein-specific enzyme inhibitor 04 (FAPI-04) is a radiolabelled molecular agent targeting the inhibitor of fibroblast activation protein (FAP), which is often present in tumor stroma and inflammatory tissue with prominent fibroblast proliferation." (PMID 34181149, 2021). "The targeting of FAP in the tumor stroma using peptide-based radiotracers is still at its outset." (PMID 34681246, 2021). "In various malignant tumors, FAP is overexpressed and has been demonstrated to participate in tumor growth and progression; therefore, efforts in the clinical translation of FAP have been made, including imaging biomarkers, prognostic value and FAP-targeted therapies." (PMID 34068501, 2021). "Since it has been shown that CAR T cells could successfully secrete BiTEs, producing anti-FAP BiTEs by CAR T cells locally in the tumor microenvironment would be on the horizon, which will be discussed later in this paper." (PMID 34177890, 2021). "In addition, targeting FAP to induce CAFs damage can also increase the penetration depth of the drug in the tumor tissue." (PMID 34490078, 2021). "Frequently, tumor progression creates an immunosuppressive microenvironment with reactive stroma positive for fibroblast activation protein (FAP) and dense extracellular matrix that forms a barrier to the immune cells (NK and CD8+ T-cells) preventing direct contact with tumor cells." (PMID 34298868, 2021). "In addition, FAP-targeting oncolytic adenovirus in tumor-bearing mice enhanced anti-tumor immunity by activating endogenous T cells to attack FAP+ stromal cells." (PMID 34305902, 2021). "However, when exposed to FAP, the nanoparticles dissociate and release the chemotherapeutic drug, which can penetrate CAFs and tumor cells." (PMID 34490078, 2021). "To verify the antifibrotic effects of nintedanib in vivo, we first evaluated whether FAP could be detected in the B16-F10 tumour stroma." (PMID 33299131, 2021). "In contrast, 68Ga-FAPI targets FAP on CAFs in the stroma of tumors, which is an indicator of desmoplastic reaction and was reported to be one of the key determinants of tumor immunity and multidrug resistance possibly related to reductions in transtumoral transport of cells and drugs." (PMID 34137945, 2021). "Moreover, the complex interactions between the tumor microenvironment components have made it difficult to precisely determine the specific contribution(s) of FAP to tumor development." (PMID 34490078, 2021). "After accumulated into the tumor tissue, scFv could specifically target FAP to inhibit the proliferation of CAFs and eliminate the physical barrier of tumors." (PMID 34906155, 2021). "FAPα overexpression has been shown to correlate with increased tumor development." (PMID 34769123, 2021).
tumor (continued). "In addition to participating in tumor growth and migration, FAP has also been reported to promote immunosuppression via STAT3-CCL2 signaling." (PMID 34068501, 2021). "Our data show that HNav-FAP could be a promising tool to enhance specific drug delivery into CAFs, thus opening new therapeutic possibilities focused on tumor microenvironment." (PMID 33562504, 2021). "Moreover, a further study used a DNA vaccine that targeted both FAP in CAFs and survivin, a critical inhibitor of apoptosis, in tumor cells." (PMID 34200702, 2021). "The timespan of tumor development of cervical lymph node metastases is certainly an important parameter for the transformation of normal fibroblasts into CAFs, and the overexpression of FAP as a target for the FAPI tracer." (PMID 33057927, 2021). "To get a preliminary evaluation of whether the functionalization allowed HFn-FAP to target CAFs in vivo, we stained tumor sections with the fibroblast marker α-SMA." (PMID 33562504, 2021). "However, FAP is overexpressed in many tumor tissues, including breast, colorectal, pancreatic, lung, brain, intrahepatic bile duct, and ovarian cancers." (PMID 34490078, 2021). "Importantly, FAP is highly expressed in CAFs, a major constituent of tumor stroma, and is upregulated in more than 90% of human epithelial cancers." (PMID 34681246, 2021). "Immunohistochemistry further confirmed that MMF‐LA@DSPE‐PEG dramatically reduced cancer‐associated fibroblast (CAF) density in tumours, as the expression levels of alpha‐smooth muscle actin (α‐SMA), fibroblast activation protein (FAP) and collagen IV were significantly downregulated." (PMID 33713546, 2021). "Instead, the super binding ability of FAP inhibitors has been widely used in tumor diagnosis." (PMID 34490078, 2021). "Ten consecutive, treatment-naïve patients (8 males, 2 females; mean age, 62 ± 9 years) with biopsy-proven OSCC underwent both whole-body [18F]FDG and [68Ga]FAPI-04 (FAP-directed) PET/CT for primary staging prior to tumor resection and cervical lymph node dissection." (PMID 34050405, 2021). "Taken together, these data suggest that the FAP-expressing subpopulation of mesenchymal stromal cells in GBMs may be involved in the formation of new blood vessels and thus enhance tumour vascularisation." (PMID 34282761, 2021). "Further studies are needed to validate our hypothesis that HNav-FAP can be employed to eradicate CAFs in combination with tumor cells-targeted therapies." (PMID 33562504, 2021). "Furthermore, immunoblot analysis revealed that FAP expression was significantly reduced in tumours from nintedanib-treated mice compared with those from control mice." (PMID 33299131, 2021). "Initially, FAP was reported to be prominently overexpressed in fibroblasts within the cancer microenvironment; however, recently, FAP expression was also discovered on tumor cells in several types of tumors." (PMID 34068501, 2021). "Similarly, fibroblast activation protein (FAP)-targeted CAR-T cells demonstrate increased cytotoxic function through reducing tumor fibroblasts in animal models." (PMID 33824268, 2021). "FAP is selectively expressed in the tumor microenvironment and is undetectable in healthy tissue." (PMID 34944738, 2021). "In univariate Cox regression using continuous values, higher FAP expression (HR = 1.01, p = 0.03, corrected P value = 1.00) and higher SPARC expression (HR = 1.07, p = 0.006, corrected P value = 0.21) in tumor stroma were associated with shorter survival in MPM patients." (PMID 33955203, 2021). "In addition, early response evaluation during and after therapy is possible with 68Ga-FAPI-PET/CT scans, as FAP is part of the tumor microenvironment and molecular changes in the tumor stroma can subsequently be depicted." (PMID 34050777, 2021).
tumor (continued). "Results from a phase I clinical study and pharmacokinetic analysis of the humanized anti-FAP antibody (sibrotuzumab) further revealed that it is well tolerated in humans and is specifically concentrated in the tumor stroma, with limited absorption in normal tissues." (PMID 34490078, 2021). "Interestingly, the opposite effect was observed when CAFs expressing FAP were therapeutically targeted, with this resulting in an impairment of tumour growth." (PMID 34298736, 2021). "In addition, the encapsulated morphology showed a significantly correlation with the T-cell exclusion pattern (p = 0.027) and increased density of FAP+ cells at the tumor margin." (PMID 34298868, 2021). "FAP targeting using FAP-based radiolabeled tracers allows the delivery of radionuclides carrying either imaging photons and/or ionizing particles (α and β+/β−) directly to tumor stroma, resulting in nuclear imaging and/or radionuclide therapy of FAP-positive tumors." (PMID 34681246, 2021). "Therefore, substantial work is needed to continue advancing our understanding of treatments targeting FAP and their anti-tumor effects." (PMID 34490078, 2021). "Furthermore, it has been proven that FAP+CAFs contribute to tumor progression, resistance to immunotherapy, and metastasis." (PMID 33996747, 2021). "The FAP-α-targeting peptide was modified on the surface to increase the targeting of tumor tissue." (PMID 34490078, 2021). "The tumor targeting of HFn-FAP was clearly appreciated by ex vivo imaging of tumors." (PMID 33562504, 2021). "Mice will be inoculated with 105 TAA1 positive tumor cells and FAP positive CAFs." (PMID 34177890, 2021). "FAP+ stromal cells, on the other hand, were present in 87.2% of tumours." (PMID 34282761, 2021). "The second hypothesis involves a direct mechanism, whereby FAP expression influences signaling pathways that control the cell cycle and proliferation, which ultimately promote tumor growth." (PMID 34490078, 2021). "The substantial association between EMA-expressing tumor cells and FAP-expressing CAF, as well as their topographical proximity, suggests that there may be interplay between tumor epithelial and stromal cells in the HCC tumor microenvironment." (PMID 34869376, 2021). "Hence, it is suggested that the role of FAP in cancer is likely to depend on cell context and tumor microenvironment." (PMID 33996747, 2021). "Thus, there is interest in FAP as a potential target for anti-tumor treatments, and existing research suggests that FAP-targeted drugs can exert curative effects in models of most solid tumors." (PMID 34490078, 2021). "Furthermore, in this model, the use of the FAP vaccine led to a reduction in tumor angiogenesis and lymphangiogenesis." (PMID 34200702, 2021). "In conclusion, our results give us confidence that the use of HNav-FAP in combination with a chemotherapeutic, would allow us to develop a double strategy with selective efficacy on CAFs and tumor cells, thus maximizing therapeutic potential and reducing side effects." (PMID 33562504, 2021). "We found that the CAFs could significantly promote tumor growth and enhance the expression of FAP and α-SMA." (PMID 34802453, 2021). "Thus, FAP is highly expressed in CAFs within tumor stroma, along with its fast and efficient internalization, rendering as an attractive biomarker." (PMID 34681246, 2021). "The promising initial clinical data on FAP-directed targeting imaging paved the way for clinical trials with a larger cohort of patients to validate the appropriateness of radiolabeled FAP-based inhibitors as pan-tumor agents." (PMID 34681246, 2021). "Similarly, another DNA vaccine against FAP constructed by Wen and colleagues also showed analogous results where its administration led to reduction in tumor growth and increased survival in tumor-bearing mice in a model of colon cancer." (PMID 34200702, 2021).
tumor (continued). "Considering that FAP is overexpressed in the tumor microenvironment and generally absent in healthy adult tissues, some research groups have sought to use FAP protease activity to selectively activate prodrugs at tumor sites to improve effectiveness and reduce toxicity." (PMID 34490078, 2021). "For example, FAP-expressing CAF have been shown to exclude T-cells from tumours through secretion of CXCL12; targeting the CXCL12/CXCR4 signalling axis using plerixafor (a CXCR4 inhibitor) has been shown to overcome this exclusion effect and promote response to anti-PD-1." (PMID 35048030, 2021). "Previous researches have shown FAP has an indirect effect on tumor cells." (PMID 34035230, 2021). "The murine model of liver cancer indicated that FAP+ cancer-associated fibroblasts (CAFs) are the main source of chemokine (C-C motif) ligand 2 (CCL2), and fibroblast STAT3-CCL2 signaling inhibited tumor growth through enhanced recruitment of myeloid-derived suppressor cells." (PMID 34490078, 2021). "Secondly, the role of FAP may be contrary to that of loss of HIF‐1α, leading to the promotion of tumour growth." (PMID 33943003, 2021). "We chose to target a set of distinct disease relevant membrane proteins—fibroblast activation protein (FAP), which is upregulated on activated fibroblasts within the tumor stroma and in fibrotic tissues, as well as programmed death-ligand 1 (PD-L1), which is strongly upregulated in many cancers." (PMID 34361120, 2021). "FAP, the main marker of CAFs, also plays an important role in tumor immunosuppression." (PMID 34305902, 2021). "Indeed, our work using mixed MCF-7 + HT-1080/FAP tumor spheroids demonstrated further enhancement of T cell stimulation by ICI." (PMID 34484225, 2021). "Therefore, activity-based probes (ABPs) for FAP have the potential to unveil several functions of FAP in the complex tumor environment." (PMID 33996747, 2021). "Diverse FAP-targeting strategies have since been developed and tested in pre-clinical models, including genetic deletion, molecular inhibitors that block FAP enzymatic activity, anti-FAP monoclonal antibodies and FAP-antigen vaccination, all with promising tumour-restraining results." (PMID 34298736, 2021). "Moreover, two novel ADCs were designed to target stroma components: tumor-associated fibroblast antigens LRRC15 and FAP (fibroblast activation protein α)." (PMID 34206707, 2021). "Moreover, there is a strong positive correlation between FAP-α and FN expression for both tumor stroma (r = 0.491, p < 0.0001) and cancer cells (r = 0.453, p < 0.0001)." (PMID 33625532, 2021). "The first hypothesis involves an indirect mechanism, whereby FAP regulates extracellular matrix remodeling that leads to enhanced tumor growth and invasion." (PMID 34490078, 2021). "The exact role of FAP in a tumorigenesis is unknown; however, its expression is related to the tumor proliferation, migration and invasion." (PMID 34638433, 2021). "As FAP is also expressed on healthy fibroblast subsets during wound repair and tissue remodeling, tumor-selective delivery by an OV may avoid toxicities." (PMID 33863363, 2021). "Besides its expression in the tumor stroma, FAP expression is also upregulated in certain malignant tumor cells, such as glioblastoma, breast, cervical, pancreatic, and colorectal cancer cells." (PMID 33996747, 2021). "In later studies by this same group, further analysis on the immune effects of this FAP-targeting DNA vaccine found a shift in the immune environment towards the more anti-tumor Th1 polarization with an increase in expression in the Th1 cytokine profile including IL-2 and IL-7." (PMID 34200702, 2021). "More recently, it was reported that FAP promotes immunosuppression through upregulation of CCL2, resulting in increased tumor growth by enhancing recruitment of myeloid-derived suppressor cells and tumor-associated macrophages." (PMID 33996747, 2021).